HDHD5 (haloacid dehalogenase like hydrolase domain containing 5)
Synonyms: CECR5
Tractability: Antibody: UniProt predicts a signal peptide or a membrane-spanning region. PROTAC: ubiquitination databases record sites on it.
Gene: Protein-coding gene on chromosome 22 (17,137,510 to 17,165,287, reverse strand). Ensembl gene ENSG00000069998.
Subcellular location (Human Protein Atlas): Mitochondria
Gene Ontology:
Cellular component: mitochondrion
Genetic constraint (gnomAD): Loss-of-function variants: 34 observed, 35.17 expected, observed/expected ratio (o/e) 0.97, 90% interval 0.74 to 1.29. The upper end of that interval is the gene's LOEUF score, 1.29, which puts it in group 5 of 6, group 1 being the genes least tolerant of losing a copy. Missense variants: 573 observed, 551.66 expected, observed/expected ratio (o/e) 1.04, 90% interval 0.97 to 1.11. Synonymous variants: 242 observed, 236.95 expected, observed/expected ratio (o/e) 1.02, 90% interval 0.92 to 1.14.
Homologues: Orthologues: chimpanzee HDHD5 (99% identical), macaque HDHD5 (94% identical), rabbit HDHD5 (82% identical), dog HDHD5 (77% identical), guinea pig HDHD5 (76% identical), mouse Hdhd5 (76% identical), pig HDHD5 (68% identical), rat Hdhd5 (61% identical), tropical clawed frog hdhd5 (53% identical), zebrafish hdhd5 (52% identical), Caenorhabditis elegans H32C10.1 (35% identical). Paralogues in human: CRLS1 (11% identical).
Diseases named in the same sentence as HDHD5 in open-access papers:
HDHD5 is named in the same sentence as 3 diseases in open-access papers, as found by Europe PMC text mining. Sharing a sentence is not in itself a finding about the gene and the disease. The quoted sentences say what the papers report.
cat-eye syndrome (4 papers, 2012 to 2024). Cat eye syndrome (CES) is a rare chromosomal disorder with a highly variable clinical presentation. "Little is known about CECR5/HDHD5 (cat eye syndrome chromosome region, candidate 5), but it is indicated as a candidate gene for a human developmental disorder called cat eye syndrome." (PMID 31075853, 2019).
HDHD5 also shares sentences with these, for which no sentence is quoted: Noonan syndrome (1 paper); tumor (1).